INS (insulin)
Diseases named in the same sentence as INS in open-access papers (continued):
Sharing a sentence is not in itself a finding about the gene and the disease.
metabolic syndrome (continued). "Metabolic syndrome is a concurrence of disturbed glucose and insulin metabolism, abdominal fat distribution, mild dyslipidemia, and hypertension, and is an important clinical condition given its association with the subsequent development of type 2 diabetes mellitus and cardiovascular disease." (PMID 27014371, 2016). "The differences in the associations between metabolic syndrome traits, beta-cell function, and insulin sensitivity in different ethnicities have not been fully explained yet." (PMID 27597980, 2016). "We compared the effects of TZD treatment on hepatic fibrosis, lobular inflammation, IR improvement, fasting serum insulin, adiposity, and dyslipidemia between the various studies using fixed and random effects models, and heterogeneity in clinical outcomes was assessed." (PMID 27759627, 2016). "This study identifies insulin sensitivity, adiposity, and dyslipidemia as logical intermediate targets for short-term physical activity trials that assess what types of physical activity may best promote metabolic health in CKD." (PMID 27876008, 2016). "Moreover, studies have shown that MHO individuals have lower levels of C-reactive protein and higher levels of insulin sensitivity, compared to obese individuals with metabolic syndrome." (PMID 27100779, 2016). "low CRP; insulin resistant v. sensitive, with orwithout the metabolic syndrome)." (PMID 27313852, 2016). "Since rice is a significant cereal option for most Asians, replacing white rice with a red rice displaying the characteristics of UKMRC9 becomes a critical factor in lowering dietary glycaemic load and insulin surge patterns attributed to the aetiology of metabolic syndrome." (PMID 27213446, 2016). "This fits with conclusions of analyses of NHANES data in relation to BMI, WC, triceps and subscapular skinfolds and insulin and to metabolic syndrome in Canadian Health Measures study, although these studies used different accelerometer protocols and comparator groups and younger samples." (PMID 26980183, 2016). "Both insulin and glucose are the major inducers of Srebf mRNA expression, and thus, these results are consistent with previous studies showing that this obesogenic diet induces GDM and metabolic syndrome, as determined by increased maternal circulating insulin, leptin, and triglyceride levels." (PMID 27555877, 2016). "Unlike glucose, fructose in serum is not regulated by insulin, and high levels of fructose consumption can cause dyslipidemia, impair glucose homeostasis and increase insulin resistance." (PMID 27074918, 2016). "This may explain the pathogenetic mechanisms of hypertension accompanied with hyperinsulinemia, edema, and fluid retention as a complication of metabolic syndrome and intensive insulin treatment." (PMID 27247938, 2016). "Indeed, indices significant for metabolic syndrome were unfavourably altered in members of Cluster II: increased concentration of insulin, proinsulin and C-peptide, along with higher LDL and lower HDL, testosterone and free testosterone." (PMID 27295977, 2016). "The transfer of intestinal microbiota from lean donors increases insulin sensitivity in individuals with metabolic syndrome, but the exact pathogenesis remains unclear." (PMID 27681909, 2016). "Based on the current literature, honey may ameliorate dyslipidemia in part via enhanced release of insulin from the remnant pancreatic β-cells." (PMID 26927161, 2016). "However, particularly hepatocellular lipid content was significantly related to clinical parameters of PCOS like whole body insulin sensitivity, dyslipidemia and free androgen index." (PMID 27505055, 2016). "The tissue distribution pattern of many connexins and their close functional connection to multiple metabolic and signaling pathways that are crucial for insulin sensitivity, lipid homeostasis and hemodynamic regulation makes them plausible candidates for metabolic syndrome pathogenesis." (PMID 27871290, 2016).
metabolic syndrome (continued). "These had an insulin decrease of 7-fold, considering dyslipidemia like in humans." (PMID 27191000, 2016). "Insulin signaling in the proximal tubule is linked to Na-HCO3 exchanger and perturbation of this pathway was proposed to be responsible for hypertension observed in metabolic syndrome." (PMID 26465605, 2015). "Recent lines of evidence have also reported improvement of insulin sensitivity after supplementation of HT-rich extracts from olive leaves in overweight men, and beneficial effects against the development of the metabolic syndrome in animal models." (PMID 26030149, 2015). "We hypothesized that daily consumption of blueberries for six weeks would be effective in improving blood pressure, endothelial function and insulin sensitivity in a population with metabolic syndrome." (PMID 26024297, 2015). "Using the level of the TG/HDL-C ratio (≥ 3.5) might be a simple method to identify insulin-resistant, dyslipidemia patients." (PMID 25635876, 2015). "The lack of insulin responses in adipocytes is a key pathogenic mechanism underlying metabolic syndrome." (PMID 25714093, 2015). "Following treatment with L-arabinose, metabolic syndrome rats had an obvious reduction in body weight, systolic blood pressure, diastolic blood pressure, fasting blood glucose, triglycerides, total cholesterol, serum insulin, TNF-α, and leptin." (PMID 26652604, 2015). "Additionally, the HFr diet not only increases insulin resistance but also promotes mild-to-severe dyslipidemia." (PMID 26090514, 2015). "Association of HbA1c, insulin, glucose, and HOMA-IR tertiles with metabolic syndrome criteria." (PMID 26241903, 2015). "Specifically, we showed the genotype TT of this SNP was associated with several metabolic traits of metabolic syndrome, including increased waist to hip ratio (WHR), fasting insulin (FINS) levels, increased serum triglyceride (TG) levels, and decreased insulin sensitivity at basal condition." (PMID 26377690, 2015). "These pigs developed symptoms of metabolic syndrome and showed cardiac steatosis and hypertrophy with a greatly increased body weight (2.73-fold, P<0.01), insulin level (4.60-fold, P<0.01), heart weight (1.82-fold, P<0.05) and heart volume (1.60-fold, P<0.05) compared with the control pigs." (PMID 26161779, 2015). "BMI-associated negative transcriptional regulation of insulin signaling and oxidative stress management provide new insights into the pathogenesis of metabolic syndrome and T2D." (PMID 26470795, 2015). "We hypothesize that HbA1c and insulin measurements, readily available in many clinical settings, could be used to improve the profiling of patients with metabolic syndrome or subjects prone to develop it." (PMID 26241903, 2015). "In addition to reducing blood glucose, an insulin-mimetic agent should be able to normalize dyslipidemia." (PMID 26445712, 2015). "The presence of chronic anovulation associated with higher androgen levels correlates with lower insulin sensitivity and higher prevalence of cardiovascular risk factors, such as IR, impaired glucose tolerance (IGT), T2DM, dyslipidemia and metabolic syndrome (MetS)." (PMID 25595199, 2015). "Subjects with first-degree relatives with T2D thus have unfavorable body composition as well as reduced insulin sensitivity, beta cell dysfunction, dyslipidemia and, at the trend level, exhibit markers of adipose tissue cell hypertrophy and dysfunction prior to developing IGT/T2D." (PMID 26407933, 2015). "Moreover, high MUFAs diet or replacement of SFAs for MUFAs induce changes in abdominal fat distribution, improve insulin sensitivity, and postprandial oxidative stress in patients with metabolic syndrome." (PMID 26055507, 2015). "Indeed, oral administration of butyrate or fecal transplantation has been shown to improve insulin sensitivity, increase energy expenditure, and reverse metabolic syndrome in mice." (PMID 26202330, 2015).
metabolic syndrome (continued). "In the absence of metabolic syndrome, insulin was more strongly associated than HbA1c to all criteria except high glucose and there were significant differences between the low- and mid-range of insulin for all criteria except high blood pressure." (PMID 26241903, 2015). "Therefore, increases in visceral and hepatic adipose tissue contribute to dyslipidemia, enhanced gluconeogenesis and insulin insistence." (PMID 27525252, 2015). "Our findings indicate presence of insulin-mimetic and anti-inflammatory actions in both peptides which may have potential applications in the management of metabolic syndrome." (PMID 25714093, 2015). "In this study we analyze cross-sectional data from the baseline visit of the Aragon Workers’ Health Study (AWHS) and compare HbA1c and insulin in their association with the metabolic syndrome and its traits in non-diabetic individuals." (PMID 26241903, 2015). "Hence, restoration of insulin actions, either by improving insulin sensitivity or by the use of compounds mimicking insulin, has been a goal for controlling metabolic syndrome and its complications." (PMID 25714093, 2015). "The risk of having left ventricular hypertrophy (crude odds ratio) for the metabolic syndrome and its different components and insulin as well as physical activity, oestrogen and percentile levels of insulin-like growth factor binding protein-1 and insulin-like growth factor-1." (PMID 25461385, 2014). "Exercise training for 8 weeks with no weight loss did not improve insulin responsiveness in euglycemic clamp studies and the baseline phosphorylation status of Ser337 and Ser636 in metabolic syndrome muscle was unchanged." (PMID 25472611, 2014). "This study examines the relationships between area-level socioeconomic position (SEP) and the prevalence and trajectories of metabolic syndrome (MetS) and the count of its constituents (i.e., disturbed glucose and insulin metabolism, abdominal obesity, dyslipidemia, and hypertension)." (PMID 24406665, 2014). "Our data showed only a small decrease in muscle IRS‐1 baseline Tyr896 phosphorylation in metabolic syndrome subjects suggesting, at least in the fasted situation, tyrosine phosphorylation was adequate (albeit with a more than two‐fold higher insulin concentration)." (PMID 25472611, 2014). "Our hypothesis was an observed reduction in BMI and secondarily in body fat content, insulin insensitivity, and other components of the metabolic syndrome in the intervention group." (PMID 25330848, 2014). "In fact, we have recently argued that periodic fluctuations in insulin in the context of the metabolic syndrome might be the “new” intermittent hypoxia." (PMID 25642193, 2014). "All of the metabolic syndrome subjects were insulin resistant." (PMID 25472611, 2014). "Furthermore improved insulin sensitivity has been found after infusion of butyrate-producing intestinal microbiota from lean donors to male subjects with metabolic syndrome." (PMID 25214711, 2014). "Eight weeks of high fructose water ingestion (F and F2 groups) resulted in a condition characterized by metabolic syndrome as indicated by the prominent increase in fasting serum glucose, serum triglyceride, serum cholesterol, and serum insulin which showed some significance at some time points." (PMID 25045706, 2014). "In a parallel study design, 47 subjects with metabolic syndrome were fed two different types of carbohydrates (a rye pasta diet with a low postprandial insulin response and an oat-wheat-potato diet with high postprandial insulin response)." (PMID 25421534, 2014). "The correlation between CTRP1 and insulin sensitivity or dyslipidemia did not guarantee the existence of the causal relationship." (PMID 24827430, 2014). "ER stress activation in the setting of the metabolic syndrome is extensively documented, and chaperone balance may regulate insulin sensitivity and glucose homeostasis." (PMID 24465394, 2014).
metabolic syndrome (continued). "This led authors to conclude that intestinal microbiota might be developed as a therapeutic agent to increase insulin sensitivity in patients with metabolic syndrome and insulin resistance." (PMID 24778627, 2014). "Alternatively, the insulin sensitizing effect may also be secondary to the recovery of dyslipidemia." (PMID 24759758, 2014). "Endothelial functions impaired in metabolic syndrome could reduce insulin access to the tissue and thus decrease insulin sensitivity independently from direct effects at the muscle cells." (PMID 24719887, 2014). "Overweight and obese youths had reduced insulin sensitivity and high prevalence of dyslipidemia.When BMI-SDS elevated up to 1.22 and BMI was higher than 21.67 in boys, dyslipidemia may happen." (PMID 23984682, 2013). "When stress is continuously undergone, an increase in adrenocortical hormones caused by hypothalamus-pituitary-adrenal axis dysregulation leads to metabolic dysfunctions such as high blood pressure, hardening of the arteries, insulin resistance, and dyslipidemia." (PMID 24472469, 2013). "In the present population-based investigation, we confirm earlier findings that FTO-mediated adiposity increases the risk of metabolic syndrome and of increased CRP, fasting insulin, and triglyceride levels; increased systolic and diastolic blood pressure; and decreased concentrations of HDL-C." (PMID 23824655, 2013). "Several previous cross-sectional studies have reported the association between iron stores and individual components of metabolic syndrome, including hypertension, dyslipidemia, elevated fasting insulin and blood glucose, and central adiposity in western countries." (PMID 24066115, 2013). "The fact that under insulin treatment optimal lipid parameters can be attained independently of the glycemic control could be fundamental because of the importance of dyslipidemias in the development of diabetic macrovascular disease." (PMID 23398881, 2013). "Finally, comparing different fat depots in the same population with nascent metabolic syndrome will help decipher their role in adipokine dysregulation, insulin resistance, and inflammation in the pathobiology of this galloping epidemic." (PMID 23653857, 2013). "The connection between metabolic syndrome and the nervous system is primarily due to insulin, which in the central nervous system plays a role in controlling neuronal function (memory and cognitive functioning), neurotransmitter release, and synaptic plasticity." (PMID 24358323, 2013). "Chronic administration of CGA inhibited hepatic G-6-Pase expression and activity, attenuated hepatic steatosis, and improved lipid profiles and skeletal muscle glucose uptake, which in turn improved fasting glucose level, glucose tolerance, insulin sensitivity, and dyslipidemia in Leprdb/db mice." (PMID 24062792, 2013). "Moreover, INPP4A gene variants were found to be associated with metabolic syndrome and asthma, and very interestingly INPP4A is also one of the insulin-signaling molecules." (PMID 23840225, 2013). "What is important to determine is whether systemic hyperinsulinemia as occurring in metabolic syndrome leads to pathophysiological changes leading to asthma, or is protective, and the mechanisms by which insulin acts on the airway." (PMID 24204385, 2013). "In addition, some processes (mainly systemic insulin resistance and inflammation) have been proposed to contribute to physiological organ remodelling and pathological damage in metabolic syndrome." (PMID 23365487, 2013). "Using a multiple logistic regression model, independent significant risk factors for subclinical atherosclerosis were identified, including age, sex, BMI, smoking status, FPG, fasting insulin, presence of hypertension, presence of dyslipidemia and lipocalin-2 or RBP4." (PMID 23799122, 2013).
metabolic syndrome (continued). "Further evidence that the lower coronary microvascular density of obese patients was independent of the metabolic syndrome was the lack of association between capillary length density and parameters of insulin sensitivity." (PMID 24312359, 2013). "We set out to test the hypothesis that genes involved in inflammation, insulin signaling and mitochondrial function would be altered in expression in the whole blood of individuals with metabolic syndrome." (PMID 24358323, 2013). "Another example of the benefits of green tea consumption is its observed effect in reducing the occurrence of T2D in both laboratory animal studies and clinical studies involving subjects with metabolic syndrome or prediabetes by improving insulin sensitivity and glucose tolerance." (PMID 24066304, 2013). "The increased risk of coronary heart disease in patients with the metabolic syndrome suggests that the insulin-resistant state is atherogenic without concomitant elevations in plasma glucose and glycosylated hemoglobin." (PMID 23251156, 2012). "In the present study, leptin and CRP levels were associated with metabolic syndrome score, indicating that high levels of these markers may be predictive of developing metabolic syndrome similarly to that shown for high baseline fasting insulin levels." (PMID 22533665, 2012). "Short-term fructose overfeeding has been shown to cause less dyslipidemia in pre-menopausal women than in men (and no change in hepatic insulin sensitivity)." (PMID 22613805, 2012). "Therefore the additional effect of berberine on dyslipidemia and plasma insulin level, which was rarely reported in conventional hypoglycaemics, should be more carefully assessed." (PMID 23118793, 2012). "Insulin is a lipid-synthetic hormone, thus alteration in a gene regulating insulin gene transcription may alter lipid metabolism as well and contribute to dyslipidemia." (PMID 23039238, 2012). "Thus, we evaluated the GLUT4 expression, insulin resistance and inflammation, characteristics of the metabolic syndrome, in an experimental model." (PMID 22897936, 2012). "In the whole series of subjects without CHC, low adiponectin levels (lower than 6 μg/ml, median value in controls) were associated with the presence of NAFLD, age, male gender, BMI, dyslipidemia, ALT, insulin levels, PNPLA3 I148M alleles (p = 0.01), and ADIPOQ genotype (p = 0.009)." (PMID 22898488, 2012). "We have hypothesized that the increased rate of DNL following consumption of fructose leads to an accumulation of hepatic lipid, which promotes dyslipidemia and decreased insulin sensitivity." (PMID 22828276, 2012). "PAI-1 levels correlate significantly with a variety of adiposity measures (BMI, waist circumference, WHR, total fat, visceral adipose tissue), and also with markers of the metabolic syndrome (inflammatory markers, insulin, glucose, triglycerides and high density lipoprotein)." (PMID 23113882, 2012). "It has been reported that abnormalities in the circulating levels of vaspin and omentin and the gene expression of both factors are related to BMI and markers of insulin sensitivity in metabolic syndrome patients, although to date, the findings of various authors are confusing." (PMID 21526992, 2011). "Moreover, because AIP is inversely correlated with insulin sensitivity, this data together suggests that the insulin-sensitizing role of Pio would provide an antiatherogenic effect by targeting atherogenic dyslipidemia." (PMID 21314919, 2011). "Additionally, a twelve-week consumption of low insulin response diet (rye bread and pasta) has been shown to enhance early insulin secretion in persons with metabolic syndrome." (PMID 21901116, 2011). "Therefore, although we do not exclude the possibility that, in Bmal1 -/- mice, impaired insulin secretion is partly responsible for development of dyslipidemia, its contribution via acceleration of lipolysis is relatively smaller." (PMID 21966465, 2011).